GSN (gelsolin)
Diseases named in the same sentence as GSN in open-access papers (continued):
Sharing a sentence is not in itself a finding about the gene and the disease.
bladder cancer (continued). "Taken together, bladder cancer patients with a down-regulated level of LAMC2 or up-regulated level of GSN were related to poor prognosis." (PMID 32640634, 2020). "In gastric cancer, gelsolin decreased EMT through inhibition of p38 signaling, while in bladder cancer gelsolin promoted carcinogenesis by inactivating the Hippo pathway leading to the nuclear translocation of Yes-associated protein." (PMID 33171868, 2020). "According to the results of survival analysis, GSN has been suggested as the most potent regulator in bladder cancer with grade 3 carcinoma." (PMID 32640634, 2020). "In bladder cancer, ATF3 suppresses metastasis of bladder cancer by regulating gelsolin-mediated remodeling of the actin cytoskeleton." (PMID 30376856, 2018). "Conversely, there is a report indicating that transfection of the GSN gene into human bladder cancer cells induced a significant decrease of tumorigenicity and colony-forming ability." (PMID 29513714, 2018). "Previous data have demonstrated that gelsolin mediated the remodeling of the actin cytoskeleton to suppress the metastasis of bladder cancer." (PMID 27419625, 2016). "Our previous data also showed that the gelsolin were decreased in bladder cancer and regulated by ATF3." (PMID 27419625, 2016). "GSN expression was knocked down in bladder cancer cell lines with two siRNA isoforms targeting GSN." (PMID 37958747, 2023). "Moreover, decreased expression of GSN appears to be an early event in bladder cancer development since reduced expression of GSN is noticed at stage one of cancer development and stays at low levels through all stages." (PMID 37958747, 2023). "Previously, overexpression of gelsolin using recombinant adenovirus encoding wild-type gelsolin (Ad-GSN) arrested cell cycle at the G2/M phase, reduced cell division in bladder cancer cells (KU-7 and UMUC-2), and inhibited tumor growth in the orthotopic bladder cancer nude mouse model." (PMID 37719007, 2023). "Conversely, GSN was categorized as a tumor suppressor in several other malignancies, in which GSN expression was reduced including, colon, non-small-cell lung, ovarian, gastric and urinary bladder cancers." (PMID 37958747, 2023). "GSN knockdown was repeated in T24 bladder cancer cells and confirmed with immunofluorescence." (PMID 37958747, 2023). "The present results demonstrate that GSN plays an important role in bladder cancer pathogenesis and may serve as a potential biomarker and therapeutic target for cancer therapy." (PMID 37958747, 2023). "The present results demonstrate that GSN plays an important role in bladder cancer pathogenesis and that targeting GSN may serve as a potential therapeutic option for cancer therapy." (PMID 37958747, 2023). "Moreover, the results revealed that down-expression of GSN is an early event in bladder cancer development and is significantly correlated with high tumor stage (stages 2, 3 and 4) of BLCA patients (p < 0.01)." (PMID 37958747, 2023). "Our finding revealed that the GSN gene is highly methylated in cancer compared to normal tissues, which explains the low expression of GSN and suggests that GSN hypermethylation may play a role in bladder cancer development." (PMID 37958747, 2023). "The TCGA data on GSN are consistent with our previous finding, suggesting that reduced GSN expression in advanced cancer (MIBC) may play an important role in bladder cancer progression." (PMID 37958747, 2023). "However, upregulated transcription factor 3 (ATF3) inhibits bladder cancer metastasis through upregulated GSN-mediated actin cytoskeletal remodeling." (PMID 37035750, 2023). "Therefore, we opted to comprehensively explore the functional significance of GSN expression in bladder cancer." (PMID 37958747, 2023). "Interestingly, we observed that GSN downregulation occurred across all molecular subtypes of bladder cancer including neuronal, luminal and basal." (PMID 37958747, 2023).
bladder cancer (continued). "Epigenetic downregulation of GSN was reported in breast and bladder carcinomas." (PMID 37958747, 2023). "In BCa, ATF3 has been found to regulate gelsolin-mediated remodeling of actin cytoskeleton to suppress tumor metastasis amd can be utilized as a potential marker of the response to histone deacetylase inhibitor mediated therapy in bladder cancer." (PMID 36396627, 2022). "The authors conclude that gelsolin may serve as an independent predictor of clinical outcomes and a novel biomarker for the early detection of head and neck cancer and in bladder cancer." (PMID 34947825, 2021). "The concentration levels of the three circulating proteins inversin, gelsolin, and apolipoprotein A1 identified high-grade bladder cancer with an AUC > 0.84 (95% confidence interval 71–98), 0.76 (95% confidence interval 61–92%), and 0.90 (95% confidence interval 82–98), respectively." (PMID 34947825, 2021). "According to the Kaplan–Meier survival curves by different mRNA expression levels of hub genes of the bladder cancer with grade 3 carcinoma, GSN, PDLIM4, and HTRA1 were identified as prognostic genes (log-rank test: p = 5.796 × 10−5; log-rank test: p = 9.952 × 10−6; log-rank test: p = 0.009244)." (PMID 32640634, 2020). "Similarly, GSN, strongly expressed in bladder cancer tissues, is a major gene for poor prognosis." (PMID 37035750, 2023). "Conclusively, GSN and LAMC2 can be candidate genes for further investigation of the molecular mechanism on bladder cancer." (PMID 32640634, 2020). "TCGA data indicated significant suppression of GSN expression in bladder cancer tissues compared to non-cancerous tissues." (PMID 37958747, 2023). "Meanwhile, for GO enrichment analysis for down regulated genes, genes such as GSN, FSCN1, and PHLDB2 were important for the invasion of many cancer types such as pancreatic cancer, bladder cancer, and colon cancer cells, but these genes may be involved in the invasion of GBM." (PMID 31137733, 2019). "Alternatively, it is possible that the GSN copy without out-of-frame ORF was not transcribed due to, e.g., acetylation, which is one of the mechanisms regulating GSN expression level in urinary bladder cancer cell lines." (PMID 34440617, 2021).
gastric cancer (19 papers, 2009 to 2025). A primary or metastatic malignant neoplasm involving the stomach. "There has been a report showing the correlation between GSN and various immune cells’ infiltration, especially dendritic cells in gastric cancer, and how decreased GSN expression is associated with poor patient outcome." (PMID 37958747, 2023). "In summary, this evidence suggests that the dysregulation of the p38 signaling pathway by gelsolin is an important mechanism that underlies gastric cancer metastasis." (PMID 27419625, 2016). "We then evaluated the association between gelsolin expression and survival in our enrolled patients with gastric cancer." (PMID 27419625, 2016). "We investigated the influence of gelsolin on gastric cancer progression as well as the mechanism that underlie its activity." (PMID 27419625, 2016). "Furthermore, lower expression of DNA methyltransferase 1 is associated with increased expression of GSN in gastric cancer cell lines (AGS)." (PMID 36291171, 2022). "Interestingly, tumor-associated M2-like macrophages could facilitate GSN methylation in gastric cancer cells to promote cancer progression." (PMID 39261905, 2024). "Tumor-associated macrophages (TAMs) were co-cultured with gastric cancer cells, and DNA methyltransferase 1 (DNMT1) expression increased; however, GSN expression decreased in gastric cancer cells." (PMID 37035750, 2023). "GSN is a tumor suppressor down-regulated in gastric cancer cells and gastric tumor tissues, and is a potential therapeutic target." (PMID 36505781, 2022). "For example, GSN is down-regulated in gastric cancer cell lines, and promoter DNA methylation is involved in this process." (PMID 35178391, 2022). "Firstly, DNMT1 overexpression was shown to methylate and silence the GSN gene, and secondly, DNMT1 overexpression was associated with higher TAMs infiltration in the TME of gastric cancer." (PMID 33535484, 2021). "A study examined the role of TAMS in DNA methylation of a tumor suppressor gene gelsolin (GSN) during gastric cancer progression." (PMID 33535484, 2021). "Scinderin and Gelsolin genes play key roles in gastric cancer initiation, progression, and invasion." (PMID 32636728, 2020). "Taken together, these results suggest that the interaction of gelsolin with PKR inhibit the PKR-p38 signaling to suppress the migration of gastric cancer cell." (PMID 27419625, 2016). "Cell adhesion assay also confirmed the inhibitory function of gelsolin on migration of gastric cancer cells." (PMID 27419625, 2016). "The correlation assay showed that loss expression of gelsolin was associated with increased phosphorylated PKR and p38 expression in human gastric cancer tissues." (PMID 27419625, 2016). "To dissect the mechanism of gelsolin on the metastasis of gastric cancer cells via EMT, we detected a series of metastasis-related proteins that were previously reported to be involved in the metastasis of gastric cancer." (PMID 27419625, 2016). "p38 inhibitor can reverse the inhibitory ability of gelsolin on the metastasis of gastric cancer cell." (PMID 27419625, 2016). "In clinical gastric cancer tissue samples, the upregulated expression levels of PKR-p38 signaling pathway proteins were associated with low levels of gelsolin, which correlated with tumor metastasis status." (PMID 27419625, 2016). "Altogether, these results highlight the importance of gelsolin in suppression of gastric cancer metastasis through inhibition of PKR-p38 signaling pathway." (PMID 27419625, 2016). "Overall, the observations of high gelsolin expression in GC tumors displaying diffusely infiltrative phenotype and low gelsolin expression in GC tumors with cohesive morphology are indicative of a positive association between gelsolin and gastric cancer invasiveness." (PMID 27058427, 2016). "We also found that gastric cancer with advanced stages (stage III and IV) had a lower gelsolin expression than gastric cancer with early stages (stage I and II)." (PMID 27419625, 2016).
gastric cancer (continued). "In gastric cancer cell, our data also showed that gelsolin modulated actin cytoskeleton remolding in MGC cell." (PMID 27419625, 2016). "In this study, our data indicated that gelsolin mediated the suppression of metastasis that can be attributed at least in part to the inhibition of PKR-p38 signaling in gastric cancer." (PMID 27419625, 2016). "To determine the function of gelsolin on gastric cancer cells, we established stable gastric cancer cell lines with over expression and knock down gelsolin constructs." (PMID 27419625, 2016). "This study aims to address the gap in knowledge between the role of gelsolin and the signaling transduction process during the metastasis of gastric cancer cells." (PMID 27419625, 2016). "The decreased expression of gelsolin has been reported in gastric cancer, however, the role and detailed mechanism of gelsolin in the pathogenesis of gastric cancer has been under explored." (PMID 27419625, 2016). "Western blot analysis revealed that p38 and phosphorylated p38 (p-p38) were negatively correlated with gelsolin expression in gastric cancer cell." (PMID 27419625, 2016). "Consistent with results obtained from wound-healing assay, over expression of gelsolin inhibited the migration of gastric cancer cells, whereas knockdown of gelsolin significantly increased migration of MGC and MKN cells by using Transwell migration assay." (PMID 27419625, 2016). "Here, we demonstrated that gelsolin was down-regulated in human gastric cancer tissues, and lower tumorous gelsolin significantly correlated with gastric cancer metastasis." (PMID 27419625, 2016). "In this work, decreased gelsolin expression in gastric cancer tissue was correlated to the lymph node metastasis and tumours invasion." (PMID 19865524, 2009). "Also, Gelsolin is down-regulated in human gastric cancer; moreover, Gelsolin significantly correlates with gastric cancer metastasis." (PMID 32636728, 2020). "In addition, TAMs promote the epigenetic silencing of gelsolin through DNA methyltransferase 1 activity induced by CCL5/CCR5/STAT3 signaling in gastric cancer cells." (PMID 31892854, 2020). "The biological function of gelsolin in gastric cancer and its mechanism remained undefined." (PMID 27419625, 2016). "Moreover, immunohistochemical staining data demonstrated that gastric cancer with lower gelsolin exhibited higher expression of p-PKR." (PMID 27419625, 2016). "Our finding indicates a role for gelsolin in the repression of gastric cancer metastasis." (PMID 27419625, 2016). "Finally, similar to the gastric cancer cell lines, PKR-p38 signaling pathway proteins tend to be activated and correlated with low expression of gelsolin in clinical gastric cancer tissues." (PMID 27419625, 2016). "However, in metastatic gastric cancer, down-regulated gelsolin releases PKR to activate p38 signaling pathway to promote the metastasis of gastric cancer." (PMID 27419625, 2016). "Western blot analysis confirmed the down-regulated gelsolin in gastric cancer tissues." (PMID 27419625, 2016). "Negative expression of gelsolin was associated with a poor outcome following surgical resection of gastric cancer in our clinical cohort." (PMID 27419625, 2016). "Taken together, our results suggest that gelsolin inhibit gastric cancer metastasis." (PMID 27419625, 2016). "Thus, it is essential to identify the function of gelsolin in gastric cancer." (PMID 27419625, 2016). "In patients with stomach cancers, GPX3, CLEC3B, CFD, GSN, and CCL14 were the leading five genes that were most significantly downregulated." (PMID 33828156, 2021). "A previous study revealed that the cytoskeletal protein GSN was a vital determinant of cell invasion and scattering by inhibiting E-cadherin expression through the HGF-PI3K-Akt signaling pathway in gastric cancer." (PMID 29175858, 2018).
gastric cancer (continued). "This study reveals for the first time a function of gelsolin in the HGF/cMet oncogenic pathway, which leads to E-cadherin repression and cell scattering in gastric cancer." (PMID 27058427, 2016). "In this study, we illustrate in detail that the p38 signaling pathway can be regulated by gelsolin to promote the process of EMT, which in turn leads to the metastasis of gastric cancer." (PMID 27419625, 2016). "However, as reported for gastric cancer, TAMs are capable of silencing TSG gelsolin in cancer cells by increased DNMT1 expression and DNA methylation of gelsolin promoter via activation of CCL5/CCR5/STAT3 signaling." (PMID 30200265, 2018). "Since diffuse GC tissues and metastatic GC cell lines revealed a possible correlation between gelsolin and tumor progression and invasiveness, we examined the effect of gelsolin on invasion in two gastric cancer cell lines with high gelsolin expression, MKN28 and AGS." (PMID 27058427, 2016). "PKR has been shown to interact with gelsolin during the innate immune response, so we tested whether gelsolin interacted with PKR in gastric cancer cells." (PMID 27419625, 2016). "We found that gelsolin expression was suppressed in gastric cancer compared to their corresponding non-tumorous tissues." (PMID 27419625, 2016). "Interestingly, when all gastric cancer samples were stratified on the basis of the status of metastasis, we found that gelsolin expression was further significantly down-regulated in gastric cancer that had metastasis, when compared with those that did not have (P<0.05)." (PMID 27419625, 2016). "To verify the relationship of gelsolin and PKR-p38 signaling pathway in human gastric cancer tissues, we detected the expression of p-PKR and PKR protein in gastric cancer and their corresponding non-tumorous tissues by Western blot." (PMID 27419625, 2016).
familial amyloidosis (17 papers, 2009 to 2026). "Combining with the literature, we discuss the clinicopathological features and predicted protein functions of mutated gelsolin, aiming to elucidate its pathogenic mechanisms and deepen the understanding of hereditary amyloidosis." (PMID 42232968, 2026). "Hereditary amyloidosis cases, such as those associated with mutations in gelsolin, cystatin C, or lysozyme, typically occur in younger individuals or as part of familial syndromes." (PMID 40700073, 2025). "In neurodegenerative diseases, gelsolin mutations are associated with familial amyloidosis, a condition in which abnormal gelsolin aggregation leads to tissue damage." (PMID 41006687, 2025). "Similarly, elevated levels of serum gelsolin have been found in gelsolin-related familial amyloidosis of Finnish type (FAF), caused by a single base mutation in plasma gelsolin, which results in impaired gelsolin-actin interactions." (PMID 30149613, 2018). "Interestingly, mutations in gelsolin are associated with the Finnish type of familial amyloidosis, a systemic disease characterized by corneal lattice dystrophy, progressive cranial neuropathy, and distal sensorimotor neuropathy in humans." (PMID 23533700, 2013). "A gelsolin gene mutation has been found in familial amyloidosis." (PMID 19367286, 2009). "The amyloid subunit in Finnish hereditary amyloidosis is derived from the actin filament-binding region of gelsolin, suggesting the involvement of defective regulation of actin dynamics." (PMID 23533700, 2013). "Mutations of GSN and ITM2B have been identified as the causes of hereditary amyloidosis." (PMID 34551193, 2021). "Hereditary amyloidosis refers to a wide spectrum of rare diseases with different causative mutations in the genes of various proteins including transthyretin, apolipoprotein AI and AII, gelsolin, lysozyme, cystatin C, fibrinogen Aα-chain, β2-microglobulin, apolipoprotein CII and CIII." (PMID 30665372, 2019). "Molecular and genetic testing can be performed in cases of hereditary amyloidosis (e.g., TTR, fibrinogen, lysozyme, apolipoproteins AI and AII, and gelsolin)." (PMID 39597824, 2024). "These proteins include amyloidogenic proteins such as gelsolin and TDP-43 that are not mutated in genetic PAMs but are mutated in hereditary amyloidosis and ALS, respectively." (PMID 31796104, 2019).